RNU6-1210P (RNA, U6 small nuclear 1210, pseudogene)
Gene: Small nuclear RNA gene on chromosome 18 (14,759,188 to 14,759,294, forward strand). Ensembl gene ENSG00000200645.
Homologues: Orthologues: chimpanzee U6 (99% identical), chimpanzee U6 (98% identical), macaque U6 (93% identical), dog U6 (69% identical), rabbit U6 (65% identical), pig U6 (64% identical), rabbit U6 (64% identical). Paralogues in human: RNU6-1207P (93% identical), RNU6-811P (92% identical), RNU6-452P (87% identical), RNU6-1293P (86% identical), RNU6-156P (86% identical), RNU6-458P (86% identical), U6 (86% identical), U6 (85% identical), RNU6-1132P (84% identical), RNU6-614P (84% identical), RNU6-666P (84% identical), RNU6-721P (83% identical), and 1293 more.